GATA3 (GATA binding protein 3)
Diseases named in the same sentence as GATA3 in open-access papers (continued):
Sharing a sentence is not in itself a finding about the gene and the disease.
neuroblastoma (continued). "Cases in the other cluster also showed a high expression of CRC-related genes in neuroblastoma, such as GATA3 and HAND2." (PMID 33465163, 2021). "Collectively, these results suggest that GATA3 plays a fundamental role in neuroblastomagenesis, and thus the transcriptional network involving GATA3 can be a hopeful target for novel neuroblastoma therapies." (PMID 33803938, 2021). "In a series of neuroblastoma cell lines, GATA3 was found to positively regulate cyclin D1 transcription by directly binding its promoter sequences." (PMID 33803938, 2021). "In contrast, the results thus far have shown that GATA3 solely functions as an oncogenic factor by transactivating cyclin D1 expression in neuroblastomas." (PMID 33803938, 2021). "Neuroblastoma-associated super-enhancers are distributed among a broad range of genomic loci of human GATA2 and GATA3." (PMID 33803938, 2021). "While expression of GATA2 and GATA3 in human neuroblastoma with relatively low malignant potential has been previously reported, their functional roles in neuroblastomas have not been assessed." (PMID 33803938, 2021). "A better understanding of how GATA2 and GATA3 function as oncogenes or tumor suppressors is of prime importance for the treatment of neuroblastoma and urothelial cancers and will shed further light on their roles as prognostic factors." (PMID 33803938, 2021). "GATA3 sense RNA expression was significantly elevated in neuroblastoma cell lines and tumours compared to normal tissues (FA, hNCC and DRG/SG)." (PMID 31831790, 2019). "Although LMO1 frequently co-occupies target loci with GATA3 in both neuroblastoma and T-ALL cells, there was little overlap among the regulated enhancers between these two cell types." (PMID 31819055, 2019). "We then proceeded to investigate GATA3 RNA and protein expression in neuroblastoma tumour tissues from different stages, to search for any relationship between in vivo biological properties of tumours and GATA3 expression." (PMID 31831790, 2019). "Knock-down of GATA3 in neuroblastoma cell lines reduced CCND1 protein and RNA expression substantially." (PMID 31831790, 2019). "Our siRNA experiments demonstrated that knock-down of GATA3 expression reduced cell proliferation and increased apoptosis in neuroblastoma cell lines." (PMID 31831790, 2019). "There was an inverse correlation between GATA3 DNA methylation and RNA expression in normal and neuroblastoma cell lines." (PMID 31831790, 2019). "In general, GATA3 sense and antisense RNA levels correlated positively, with N-type neuroblastoma cells generally having the highest antisense expression." (PMID 31831790, 2019). "We therefore went on to examine the DNA methylation, expression and functional relevance of GATA3 in neuroblastoma." (PMID 31831790, 2019). "Almost all neuroblastoma tumours expressed detectable GATA3 protein, of which 61% expressed higher levels than FA." (PMID 31831790, 2019). "This suggests that the GATA3 transcriptional network is a promising target for novel neuroblastoma therapies." (PMID 31831790, 2019). "The exceptions were SH-EP and GI-ME-N, S-type neuroblastoma cell lines, which had some GATA3 methylation and low RNA expression." (PMID 31831790, 2019). "Overall, there was a good correlation between GATA3 RNA and protein expression in the neuroblastoma cell lines." (PMID 31831790, 2019). "We have now shown that GATA3, an important regulator of sympathetic nervous system development, is hypomethylated in neuroblastoma cell lines and tumour tissues." (PMID 31831790, 2019). "Specific methylation assays confirmed the hypomethylation of GATA3 in neuroblastoma, which correlated with high expression at both the RNA and protein level." (PMID 31831790, 2019). "In neuroblastoma, Gata3 is reported to activate Cyclin D1 and promote proliferation, whereas silencing of Gata3 induces differentiation." (PMID 27531972, 2016).
neuroblastoma (continued). "The current study showed that high GATA3 expression was correlated with poor survival in patients with neuroblastoma." (PMID 25351211, 2015). "The present study investigated the role of GATA3 in neuroblastoma proliferation and differentiation." (PMID 25351211, 2015). "In conclusion, the present results confirmed that GATA3 has an important function in neuroblastoma differentiation and proliferation." (PMID 25351211, 2015). "Overexpression of GATA3 expression significantly increased cell growth and self-renewal in neuroblastoma cells." (PMID 25351211, 2015). "Retinoic acid treatment led to GATA3 downregulation together with neuronal differentiation, suppression of cell proliferation and inhibition of tumorigenecity in neuroblastoma cells." (PMID 25351211, 2015). "The correlation between GATA3 expression levels and prognosis in primary neuroblastoma was investigated using the Seeger microarray dataset, which is available from the online Oncogenomics database." (PMID 25351211, 2015). "Furthermore, expression of several genes associated with glioblastoma (STAT3, PDGFRA, MET, and NF1) and neuroblastoma (GATA3, ISL1, LMO1, and LIN28B) progression was downregulated at the transcriptional level in differentiated cells." (PMID 39859209, 2025). "However, some studies link increased GATA3 expression to a more favorable prognosis in tumors such as neuroblastoma." (PMID 37829946, 2023). "Furthermore, it is conceivable that GATA2 and GATA3 play a fundamental role in the genesis of neuroblastoma, given their roles in normal sympathoadrenal development." (PMID 33803938, 2021). "Considering that GATA2 also participates in sympathoadrenal development, it would be important to elucidate whether GATA2 plays a role in the genesis and maintenance of neuroblastoma, as does GATA3, under similar regulatory mechanisms." (PMID 33803938, 2021). "Moreover, protein expression of ALK, MEK6 and GATA3 was increased after regorafenib treatment, suggesting potential mechanisms for neuroblastoma cell resistance to regorafenib." (PMID 32457362, 2020). "In neuroblastoma, GATA3 plays a central role in regulating LMO1 expression." (PMID 32128448, 2020). "Therefore, the GATA3 transcriptional network is a promising target for novel neuroblastoma therapies." (PMID 31831790, 2019). "Thus, one of the likeliest mechanisms by which GATA3 affects cell proliferation in neuroblastoma, is via regulation of its transcriptional target cyclin CCND140,54, which when knocked-down, shows similar effects on cell proliferation to GATA353." (PMID 31831790, 2019). "In addition, GATA3 was known to be of importance in development of sympathetic nervous tissue, from which neuroblastoma derives." (PMID 31831790, 2019). "IMR32, Kelly and NGP neuroblastoma cell lines, all of which expressed high levels of GATA3 sense RNA and GATA3 protein, were transfected with siRNAs to knock-down GATA3 expression, and then cell proliferation and cell death were assessed by a variety of assays." (PMID 31831790, 2019). "This suggested that one of major mechanisms by which GATA3 affects neuroblastoma cell proliferation may be via modulating CCND1 levels." (PMID 31831790, 2019). "Interestingly, our results identified GI-ME-N and SH-EP as the only two neuroblastoma cell lines that had GATA3 DNA methylation, like hNCC, with corresponding low levels of expression of GATA3 protein." (PMID 31831790, 2019). "GATA3 protein was overexpressed in nearly all neuroblastoma cell lines compared to normal tissue." (PMID 31831790, 2019). "The current study provided a number of lines of evidence to support the hypothesis that GATA3 acts as an important mediator of neuroblastoma differentiation." (PMID 25351211, 2015). "In addition, GATA3 markedly upregulated the self-renewal ability, including the colony forming and sphere forming capability, of neuroblastoma cells." (PMID 25351211, 2015).
neuroblastoma (continued). "The present study aimed to define whether GATA3 is involved in the differentiation of neuroblastoma cells." (PMID 25351211, 2015). "Furthermore, the RA-induced neuroblastoma differentiation was accompanied by GATA3 downregulation and the upregulation of peripherin, a neuronal differentiation marker." (PMID 25351211, 2015). "The expression of GATA3 in various neuroblastoma cell lines was examined." (PMID 25351211, 2015). "Since GATA2 and GATA3 are both involved in a complex transcription factor network regulating sympathoadrenergic traits, the frequent occurrence of super-enhancers in GATA2 and GATA3 loci appears to underlie the sympathetic noradrenergic cell identity of neuroblastoma cells." (PMID 33803938, 2021). "In this regard, the GATA3-specific deoxyribozyme (single-stranded synthetic DNA antisense molecules) that has been successfully applied to allergic asthma patients in recent phase 2a clinical trial may exert some efficacy against neuroblastoma." (PMID 33803938, 2021). "To assess whether GATA3 knock-down might be affecting cellular differentiation, we investigated the expression of a range of differentiation markers in the siRNA-transfected neuroblastoma cell lines." (PMID 31831790, 2019). "We therefore investigated whether DNA methylation affected GATA3 expression in neuroblastoma." (PMID 31831790, 2019). "Therefore, GATA3 may be useful as a prognostic marker in patients with neuroblastoma, and may also serve as a potential therapeutic target for neuroblastoma." (PMID 25351211, 2015). "This suggests that GATA3 may be used as a prognostic marker in neuroblastoma." (PMID 25351211, 2015). "These NIPBL-bound MYCN peaks are highly enriched for motifs of core regulatory circuitry (CRC) transcription factors such as GATA3, PHOX2A, HAND1, and HAND2, which contribute to the maintenance of the neuroblastoma oncogenic cell identity." (PMID 40867243, 2025). "However, while we did demonstrate that GATA3 does not bind to the TATA allele at rs2168101 in human neuroblastoma cell lines, our findings in the zebrafish did not directly demonstrate that GATA3 could not bind to the TATA sequence at this locus." (PMID 37183825, 2023). "Surprisingly, ASCL1 deletion had little effect on the transcription of CRC gene transcripts in these neuroblastoma cell lines, but the ability of MYC/MYCN and CRC component proteins, PHOX2B and GATA3, to bind to chromatin was compromised." (PMID 36263020, 2022). "These include increased dependencies on ISL1, GATA3, and MYCN in neuroblastoma, all of which were recently reported as part of the core regulatory circuitry (CRC) in neuroblastoma and associated with superenhancers." (PMID 35382456, 2022). "The adrenergic CRC consists of an interdependent autoregulatory network that includes HAND2, ISL1, PHOX2B, GATA3, ASCL1, and TBX2 and is essential to drive the expression of MYCN and to facilitate the growth and survival of MYCN-amplified neuroblastoma cells." (PMID 34669465, 2021). "Gene expression levels for the adrenergic neuroblastoma CRC members—MYCN, HAND2, ISL1, PHOX2B, GATA3, ASCL1, and TBX2—were assayed by quantitative RT-PCR at 1, 3, and 6 days after treatment with 5 μM ATRA." (PMID 34669465, 2021). "ADRN-type neuroblastoma, showing sympathetic noradrenergic identity, was characterized by CRC modules formed by several transcription factors, such as HAND2, PHOX2B, and GATA3, leading to high expression of these genes." (PMID 33465163, 2021). "Transcription factor ChIP-seq in MYCN-expressing cells confirmed that four of the enhancers (e1, e2, e4, and e5) were bound by each of three noradrenergic neuroblastoma core regulatory circuit transcription factors (PHOX2B, HAND2, GATA3)." (PMID 33199677, 2020). "It is intriguing that LMO1 participates as a cofactor in CRCs containing GATA3 in both T-ALL and neuroblastoma; however, the remainder of the CRC of T-ALL and neuroblastoma remain completely distinct." (PMID 31819055, 2019).
neuroblastoma (continued). "Regulatory elements controlling ASCL1 expression are bound by LMO1, MYCN and the transcription factors GATA3, HAND2, PHOX2B, TBX2 and ISL1—all members of the adrenergic (ADRN) neuroblastoma core regulatory circuitry (CRC)." (PMID 31819055, 2019). "To further investigate the possible pathways by which GATA3 influences neuroblastoma proliferation, we examined cyclin D1 (CCND1), one of the known targets of GATA3 that is involved in cell cycle regulation." (PMID 31831790, 2019). "Knockdown of GATA3 results in decreased LMO1 expression and suppression of neuroblastoma cell growth." (PMID 29445148, 2018). "The expression of GATA3 was also investigated in the SHEP1 cell line, which is a benign neuroblastoma cell line with a highly differentiated status." (PMID 25351211, 2015). "Likewise, GATA3 can be overexpressed in pancreatic cell lines and primary pancreatic cancers, and in neuroblastoma cell lines, where it positively regulates cyclin D1, maintaining cells in an undifferentiated state, therefore suggesting an oncogenic potential for GATA3 in neuroblastoma." (PMID 24205108, 2013). "Neuroblastoma derives from embryonic neural crest cells, and in NB tumors that harbor amplification of the proto-oncogene MYCN, a transcriptional core regulatory circuitry (CRC) that includes MYCN, HAND2, ISL1, PHOX2B, GATA3, and TBX2 promotes tumorigenesis." (PMID 40766465, 2025). "Indeed, MYCN, ISL1, HAND2, and PHOX2B, together with GATA3 and TBX2, comprise the core regulatory circuit, an autoregulatory transcriptional loop that maintains the malignant phenotype of MYCN-positive neuroblastoma." (PMID 37297004, 2023). "Among these, selective essentiality for GATA3 was only observed for high-NE-score neuroblastoma cell lines but not SCLC cell lines, whereas BCAR1 appears to be a shared vulnerability for low-NE-score cell lines in both neuroblastoma and SCLC." (PMID 37255415, 2023). "The adrenergic identity of the ADRN subtype of neuroblastoma cells is maintained by a transcriptional core regulatory circuit (CRC) of predominantly developmental regulators of neurogenesis including PHOX2B, GATA3 and ASCL1, whose expression is further maintained by high levels of MYC or MYCN." (PMID 36263020, 2022). "To further test the hypothesis that ASCL1 regulates chromatin accessibility of these transcription factors, we utilised publicly available PHOX2B and GATA3 ChIP-seq datasets in parental BE2C and Kelly neuroblastoma cell lines." (PMID 36263020, 2022). "Notably, this identified motifs with high similarity to the known binding motifs of several neuroblastoma core regulatory circuit transcription factor motifs including HAND2, GATA3 and PHOX2B." (PMID 36263020, 2022). "Our results therefore show that GATA3 is essential for the sustained proliferation of adrenergic neuroblastoma cells, but not solely responsible for defining their lineage." (PMID 31831790, 2019). "However, there was very little overlap in these LMO1-bound regions between Kelly neuroblastoma and Jurkat T-ALL cells, indicating that LMO1 and GATA3 bind different lineage-specific enhancers." (PMID 31819055, 2019). "Consistently, FLAG-tagged LMO1 could interact with endogenous GATA3 and LDB1 proteins when overexpressed in Kelly neuroblastoma cells." (PMID 31819055, 2019). "We found that knock-down of GATA3 decreased CCND1 expression in neuroblastoma cell lines and that in tumour samples, there was high expression of CCND1 compared to FA and a good correlation between GATA3 and CCND1 expression, as found by others." (PMID 31831790, 2019). "In neuroblastoma tumours, most showed increased expression of CCND1 compared to FA, where it was undetectable and there was a good correlation between GATA3 protein expression and CCND1 protein expression." (PMID 31831790, 2019). "Our results showed that a complete absence of GATA3 DNA methylation and a high level of GATA3 protein expression, were both indicators of poor prognosis in neuroblastoma." (PMID 31831790, 2019).
neuroblastoma (continued). "Neuroblastomas that had completely absent GATA3 methylation and/or very high levels of protein expression, were associated with poor prognosis." (PMID 31831790, 2019). "This analysis indicated that GATA3 is a prognostic marker in neuroblastoma, which is independent of the status of MYCN amplification." (PMID 25351211, 2015). "Although FOG-2 is likely to interact with any GATA protein, our data obtained in neuroblastoma specimens suggest a predominant interaction with GATA-2 and/or GATA-3; in addition, the interaction between FOG-2 and GATA-4 could be disturbed." (PMID 19707195, 2009). "This variant was found to be located in open chromatin regions identified in 29 ATAC‐seq and 5 H3K27ac ChIP‐seq experiments in various neuroblastoma cell lines, but also showed the highest enrichment of TF binding sites, including MYCN, LMO1, GATA3, HAND2, ISL1, PHOX2B, and TBX2." (PMID 40525640, 2025). "In almost all neuroblastoma cell lines, there was little or no GATA3 DNA methylation, and much higher levels of expression of both the sense and antisense GATA3 RNAs, compared to normal tissues (FA, hNCC and DRG/SG), which had 7–22% DNA methylation, and very low RNA expression." (PMID 31831790, 2019). "However, we found that knock-down of GATA3 did not alter the differentiation status of the three neuroblastoma cell lines tested." (PMID 31831790, 2019). "We assayed markers of both mesenchymal differentiation (VIM, PRRX1 and SNAI1) and adrenergic differentiation (NCAM, NF68), but observed no reproducible changes in gene expression, suggesting that GATA3 knock-down only affects proliferation and death, but not differentiation, in neuroblastoma cells." (PMID 31831790, 2019). "Published chromatin immunoprecipitation sequencing (ChIP-seq) experiments in neuroblastoma lines show binding of GATA2 and GATA3 to cRE1 and cRE3, but not cRE2 1,32." (PMID 37386251, 2023). "TBX2 (T-box 2 transcription factor) is a constituent of the NOR CRC in neuroblastoma cells, together with HAND2, GATA3, and PHOX2B." (PMID 34200747, 2021).